VWF (von Willebrand factor)
Diseases named in the same sentence as VWF in open-access papers (continued):
Sharing a sentence is not in itself a finding about the gene and the disease.
tumor (continued). "ECs-released VWF fibers markedly bind platelets, forming aggregates that may protect cancer cells from immune cells, or may directly influence tumor extravasation of activating-ECs factors." (PMID 29884885, 2018). "Thus, our data indicated that vWF dysregulation was the critical mediator that contributed to tumor suppression induced by miR-24." (PMID 30279208, 2018). "This study demonstrated that targeting the interaction among collagen, vWF, and GPIbα in cancer therapy could attenuate the metastatic potential of tumor cells." (PMID 30223883, 2018). "Various ligands of GPIbα, such as vWF, thrombin, and P-selectin, are all essential for metastasis-promoting activity of platelets, resulting in a complex role of GPIbα in the process of tumor cell metastasis." (PMID 30223883, 2018). "VWF expressing cancer cells were also detected in patient tumor samples of varying histologies." (PMID 28035064, 2017). "In direct contrast to this supposition, however, there are studies indicating that vWF may play an anti-tumor role." (PMID 29299165, 2017). "Additionally, VWF fibers in tumor vasculature were shown to mediate platelet aggregation and contribute to melanoma metastasis." (PMID 28035064, 2017). "Although these analyses were performed on only a few tumor samples in situ, our results underscore the physiological relevance of endogenous VWF expression by cancer cells since they demonstrate that this phenomenon is not restricted to cancer cell lines grown in vitro." (PMID 28035064, 2017). "An association between an enhanced risk of thrombotic complications and an increase of von Willebrand factor (VWF) levels in plasma and tumor tissue of patients with distinct malignancies has been described by multiple clinical studies for specific malignancies." (PMID 27602496, 2016). "Previous findings have raised the question of whether VWF plays a pro- or anti-metastatic role in hematogenous tumor progression." (PMID 27602496, 2016). "Notably, the tumor cell-induced release of VWF from HUVECs (52.6 ± 3.1 ng/ml) was twice that from LECs (24.3 ± 3.0 ng/ml)." (PMID 27602496, 2016). "In addition to the crucial physiological effects of VWF in vessel repair, the release of VWF from intact, undamaged ECs can be induced by tumor cells." (PMID 27602496, 2016). "Intradermal tumor cell inoculation in VWF- and ADAMTS13-deficient mice did not alter lymph node metastases compared with wild type animals." (PMID 27602496, 2016). "To evaluate whether tumor cells stimulate the exocytosis of VWF in the lymphatic endothelium in vitro, we performed immunofluorescence studies and enzyme-linked immunosorbent assays (ELISAs)." (PMID 27602496, 2016). "Notably, ADAMTS13 deficiency resulted in a prolonged lifetime for VWF fibers associated with higher vessel density and size, thus supporting a role of EC activation and luminal VWF networks in tumor angiogenesis." (PMID 27602496, 2016). "As expected, a VWF deficiency was characterized by a lack of VWF in the vessel wall and of the luminal fibers of the tumor vessels (data not shown)." (PMID 27602496, 2016). "In our lymphatic tumor model, neither VWF deficiency nor ADAMTS13 deficiency had a significant effect on primary tumor development and metastasis formation." (PMID 27602496, 2016). "In patients with GBM, survival was inversely related to VWF:Ag levels and tumor volume." (PMID 27236861, 2016). "In addition, IHC detected remarkably higher levels of vWF protein expression concentrated in the tumor stroma region." (PMID 25886574, 2015). "The data from this study not only provide novel insights into the likely role of vWF in GC pathogenesis, but also highlight the potential clinical significance of serum vWF and tumor-related mRNA and protein expression as markers of disease stage and prognosis." (PMID 25886574, 2015). "Beyond its role in hemostasis, vWF has emerged as a pivotal regulator of tumor cell metastasis." (PMID 26306290, 2015).
tumor (continued). "The patient presented an elevated Von Willebrand factor that can be attributable to tumor activity, whereas the antithrombin III level near the lower limit of the normal range may represent an effect of enoxaparin." (PMID 25810936, 2015). "The higher mRNA and protein expression of vWF in GC tumor stroma may be regulated by the VEGF-VEGFR2 signaling pathway in vitro and may contribute to GC progression in vivo." (PMID 25886574, 2015). "Interestingly, the expression of FVIII protein was expressed in microvascular of tumor stroma region, and consistent with the expression of vWF protein." (PMID 25886574, 2015). "von Willebrand factor (vWF) is a potent regulator of angiogenesis, tumor growth, and metastasis." (PMID 25886574, 2015). "While a subsequent study of tumor angiogenesis characterized vWF staining as an effective clinical maker of microvessel density, suggesting its clinical utility as a prognostic marker of cancer progression or patient survival, its roles in GC have not yet been fully characterized." (PMID 25886574, 2015). "Additionally, high vessel density (measured as expression of von Willebrand factor) and decreased tumor stromal expression of Caveolin-1 was related to bad prognosis." (PMID 24505269, 2014). "PLTs efficiently shield and protect malignant cells from the host’s immune system and provide a useful medium for the adhesion of cancer cells to the vascular endothelium through forming tumor thrombi and adhesion molecules, including P-selectin and von Willebrand factor." (PMID 24944610, 2014). "Also, von Willebrand factor is increased in cancer patients and has been correlated to advanced tumor state." (PMID 25186061, 2014). "Therefore the expression of CD34 and vWF, molecular markers of vascular endothelial cell, in tumor and heart tissue sections was further evaluated by IHC." (PMID 24903055, 2014). "Together with VWF, which is downregulated in tumor endothelial cells of CRC, CYP1B1 over-expression could promote angiogenesis in colon hepatic metastases." (PMID 24023955, 2013). "In addition, iron positive cells colocalized with ongoing tumor angiogenesis and expressed human endothelial markers vWF and CD31." (PMID 22662174, 2012). "Three separate αHS clones (AO4B08, EV3C3, and HS4E4) preferentially stained for HS epitopes localized to the tumor vasculature, i.e. αHS showed strong co-localization with the EC markers von Willebrand factor (vWF) and integrin αvβ3, the latter being a known marker of activated endothelium." (PMID 23152853, 2012). "The tumor sections were also analyzed immunohistochemically using anti-vWF antibody." (PMID 22448259, 2012). "VWF might participate in the interaction of tumor cells with the subendothelium, and appears to obstruct metastasis by reducing sustained adherence of malignant cells in the microvasculature at the target organ." (PMID 21470136, 2011). "Pharmacodynamic (PD) evaluations of vascular-disrupting activity were performed, including measurement of plasma von Willebrand factor (vWF) and circulating endothelial cells (CECs), and assessment of the tumour microvasculature with dynamic contrast-enhanced magnetic resonance imaging (DCE-MRI)." (PMID 20733579, 2010). "Interestingly CD 34 in all tumor vascular endothelial cells was undetectable and VWF expression was remarkably variable among tumor vascular endothelial-like cells." (PMID 18286204, 2008). "However, little CD45+, CD31+, CD34+, and VWF+ cells were detected among tumor endothelial-like cells." (PMID 18286204, 2008). "In all tissue and tumor RNA samples assayed, vWF mRNA was detectable." (PMID 15294024, 2004). "The density of CD34+ vWF- or CD141+/vWF- vessels could thus reflect the rate tumour angiogenesis and the consequences it has for the biological behaviour of DCIS." (PMID 11953822, 2002). "At the same time, low levels of ADAMTS13 may enhance the pro-tumor effects of VWF." (PMID 40699668, 2025).
tumor (continued). "Factors such as impaired liver function, chronic liver inflammation, fibrosis, cirrhosis, increased systemic inflammation, tumor-associated cytokines (e.g., IL-6, TNF-α), tumor hypoxia, and elevated VWF levels in HCC may also contribute to a relative deficiency of ADAMTS13." (PMID 40699668, 2025). "VWF may facilitate tumor cell adhesion to the endothelium and subsequent metastasis." (PMID 40699668, 2025). "The enhancement role of VWF in cancer metastasis was proposed to involve several mechanisms, such as facilitating tumor cell adhesion to EC, increasing vascular permeability for cancer cell extravasation, stimulating angiogenesis to promote tumor growth, and supporting leukocyte recruitment." (PMID 39282473, 2024). "Moreover, antibodies directed against α-SMA actin, myosin, and desmin are commonly included to discriminate among mesenchymal tumours deriving from smooth and skeletal muscles while antibodies for Von Willebrand factor are used to recognize haemangioma/haemangiosarcomas." (PMID 37525233, 2023). "In addition, we found downregulated expression of ATP2A3, VWF in tumor tissues." (PMID 37091788, 2023). "Low ADAMTS-13 activity could result in elevated levels of highly polymeric von Willebrand factor (vWF), which might facilitate adhesive interactions with both circulating tumor cells and platelets, resulting in thrombus formation and the presumptive development of a metastatic colony." (PMID 36474619, 2022). "VWF may also promote the transformation of tumor cells to facilitate metastasis as well." (PMID 35327035, 2022). "Intriguinglytumors may also sequester circulating vWF from plasma into the tumor stroma." (PMID 35814405, 2022). "Further studies to determine whether tumor-released VWF can be differentiated from an endothelial cell, and a platelet-derived VWF on peripheral blood sampling will likely improve the specificity of the VWF as a biomarker." (PMID 35327035, 2022). "Perhaps tumor directed therapy, rather than systemic therapy, such that VWF/ADAMTS13 is only altered in the tumor microenvironment, may assist with mitigating this risk." (PMID 35327035, 2022). "•Increased levels of highly adhesive VWF may regulate platelet-tumour interactions." (PMID 33571850, 2021). "In addition, immunohistochemical staining showed significantly elevated expression of fibrinogen and vWF in the vessels and interstitium of lungs in 4T1 tumor-bearing mice compared with normal control mice, but were significantly attenuated by dunnione and nadroparin." (PMID 34769515, 2021). "Furthermore, the VWF multimers may serve as a bridging platform that tethers platelets and tumour cells to form heterotypic aggregates, promoting cancer metastasis by facilitating transendothelial migration across the blood vessel wall." (PMID 33571850, 2021). "Cancer cell metastasis could be reduced by inhibiting cancer cell-derived VWF in tumor cells." (PMID 34582363, 2021). "•VWF may protect disseminated tumour cells from chemotherapy." (PMID 33571850, 2021). "Hence, CD34 and VWF upregulation could be involved in abnormal vasculogenesis during tumor regrowth." (PMID 31803626, 2019). "Therefore, VWF may be an important adhesion protein involving in thromboembolism and tumor metastatic process." (PMID 29152610, 2017). "This phenomenon may be related to tumor-derived vascular endothelial growth factor (VEGF) secretion, which mediates endothelial cell activation and, therefore, promotes VWF expression in the tumor vessel lumen—a biological process, which promotes platelet recruitment and atheroembolism." (PMID 29164134, 2017). "Moreover, tumor angiogenesis directly correlates with intraluminal VWF fiber formation." (PMID 27602496, 2016).
tumor (continued). "In the present study, we found that a lower level of VWF protein, a marker of vascular endothelial cells, was observed in the tumor isolated from the FA-treated mice as compared with those isolated from the vehicle-treated mice, suggesting that tumor angiogenesis was reduced in FA-treated mice." (PMID 26056802, 2015). "Assessment of tumor vascularity by counting vWF-positive tumoral vessels distinct from tumoral vWF-expressing CEPs, also detected by the antibody used, additionally showed that TAM reduction was associated with significantly reduced numbers of capillaries throughout the tumor (p < .03)." (PMID 19522014, 2009). "Among them, it was interesting to note that the antitumour efficacy of the triple combination could be attributed both to a direct impact on tumour cell proliferation (Ki67 with a marked decrease in labelling) and on the endothelial cell network of the tumour (vWF staining)." (PMID 17592499, 2007). "The discovery that vWF-normalized mouse HIP mRNA levels were markedly decreased in A549 tumors and undetectable in all of the PC3 tumors we examined gives further weight to the hypothesis that decreased HIP expression is associated with tumor angiogenesis." (PMID 15294024, 2004). "The corresponding heatmap depicted the high-expression profiles of various cell types in marker genes such as KRT19, VWF, ACTA2, CD68, and TPSB2, effectively distinguishing immune, stromal, and tumor cell components." (PMID 41488617, 2025). "Upon tumor-induced activation, they serve as major transporters of VEGF, which triggers the release of von Willebrand factor (vWF) and subsequent secretion of PDGF, TGF-β, and angiopoietin-1 (ANGPT-1)." (PMID 41383620, 2025). "Several hub genes, such as CDH5, CLDN5, VWF, and PECAM1, were significantly upregulated, reflecting their established involvement in vascular development and tumor progression." (PMID 41008787, 2025). "Immunostaining for endothelial markers (vWF and CD31) revealed the spatial organization of HUVEC cocultures as surrounded by tumor cells." (PMID 41310721, 2025). "The results showed a pattern in which PECAM1, VWF, CXCR4, and CXCL12 appeared to infiltrate regions of the tumor delineated by HE staining and EPCAM." (PMID 39965034, 2025). "Other OPG ligands, e.g. TRAIL (Tumor necrosis factor Related Apoptosis-Inducing Ligand), glycosaminoglycans, proteoglycans, and von Willebrand factor/factor VIII complex, are involved in vascular, immune, and tumor pathophysiology." (PMID 40775369, 2025). "Stromal cells lack endothelial markers (i.e., vWF, CD31, and CD34), which highlight the tumor’s vascular network." (PMID 41153937, 2025). "Recent studies on tumor-derived EVs show they can modulate gene expression in endothelial cells, promoting VEGF, VWF, VEGFR2, CXCL5, and CCR1 expression and enhancing endothelial cell proliferation and migration." (PMID 40141288, 2025). "The majority of tumor cells being arrested at arterio-venous junctions has been observed in a zebrafish model, which may be due to the elongational flow induced VWF extension and activation to recruit platelets and tumor cells under physiological flow rates at these sites." (PMID 39282473, 2024). "We assume that, in our setting, the tumor cells attract and activate platelets through either tumor cell podoplanin-platelet CLEC-2 or tumor cell integrin-vWF-platelet GPIb interactions." (PMID 38764040, 2024). "Platelet activation and subsequent platelet-tumor cell adhesion is triggered through a diverse array of factors released by tumor cells, including thrombin, ADP, and vWF." (PMID 39114075, 2024). "This single cell transcriptomic analysis allowed us to identify the presence of macrophages (CD163), T cells (CD3D), and pericytes (PDGFRB), as well as endothelial (VWF) and folliculostellate (SOX2) cells, within the tumor microenvironment." (PMID 39217365, 2024).
tumor (continued). "The pro-tumoral properties of ADAM17, VWF, and EDN1 have been well-studied in the literature, and targeted therapy has demonstrated the effects of tumor-inhibiting." (PMID 36902193, 2023). "According to the data on THPA, most of these genes (VWF, GNG11, FGF7, and IL3RA) were also higher in PAAD tissues at the protein level (compared to non-tumor tissues)." (PMID 37070074, 2023). "Multiplex IHC staining further verified the existence of EndMT ECs co-expressing VWF and α-SMA in tumor tissues." (PMID 37853464, 2023). "To verify that, we selected 3 SC-matched tumor-peritumor tissue slices (covering 3 tumor types), and detected intermediate-state sub-cluster C5 marker (CPE) and two EC co-localization markers (VWF and STAB2) using RNAscope ISH." (PMID 37985711, 2023). "The expression levels of MMP9, VWF, VEGFA, SERPINE1, and TIMP1 in ccRCC tissues were higher than those in normal tissues, while the expression of EGF in tumor tissues was lower." (PMID 36959648, 2023). "In 2020, Aslan Mansurov reported a vWF A3 CBD-IL-12 fusion protein, which was also improved with better anti-tumor effect and fewer toxicities in C57BL/6 B16F10 and EMT6 allograft mouse models." (PMID 37692860, 2023). "Tumor cells express positivity with endothelial markers such as CD31, CD34, ERG, and von Willebrand factor (VWF)." (PMID 34757619, 2023). "Jun Ishihara and colleagues reported a fusion protein of IL-2 and vWF A3-CBD, which reduced splenomegaly and pulmonary edema induced by IL-2-related vascular leakage and improved its anti-tumor efficacy in C57BL/6 B16F10 allograft mouse model." (PMID 37692860, 2023). "Immunohistochemical results showed that the expression levels of CD31, PDGFB, VEGF, VWF, and PDGFRB in the HCC-PDX tumor tissues were all downregulated by MTE in a dose-dependent manner." (PMID 35847002, 2022). "It is thought that the accumulation of UL-VWF and downregulated ADAMTS13 levels lead to VWF-platelet aggregates and fibrin deposition in the tumor vasculature resulting in a prothrombotic milieu in certain disseminated malignancies." (PMID 35327035, 2022). "VWF and ADAMTS13 have been explored as tumor biomarkers for the detection and prognostication of certain malignancies; however, the results are underdeveloped and so currently not utilized for clinical use." (PMID 35327035, 2022). "It is likely that VWF and ADAMTS13 promote tumor metastasis via interactions and effects on endothelial cells, platelets and the tumor microenvironment." (PMID 35327035, 2022). "For example, tumor cells showed particularly high expressions of KRT8, KRT18 and TCF7L1, whereas endothelial cells showed particularly high expressions of PECAM1 and VWF.." (PMID 35494058, 2022). "Tumor-derived VEGF mediates endothelial cell activation, vWF release, and platelet aggregation thereby provoking the coagulation cascade in patients with melanoma cancer." (PMID 34322381, 2021). "The first group included CA9, NDUFA4L2, EGLN3, BHLHE41, VWF, IGFBP3, and ANGPTL4, whose expression levels were coordinately decreased during tumor progression." (PMID 34046336, 2021). "A fusion protein (CBD-CCL4) of chemokine CCL4 and the collagen-binding domain (CBD) of von Willebrand factor (VWF, specifically the A3 domain) was able to recruit CD103+ DCs into the TME and promote the anti-tumour immune response." (PMID 33917287, 2021). "At the initial stage of tumor development, BHLHE41 expression correlated with that of VWF and IGFBP3 expression." (PMID 34046336, 2021). "Tumor growth is promoted by activating proliferation (BHLHE41, VWF, ANGPTL4, and possibly IGFBP3), and preventing the apoptosis of cancer cells (ANGPTL4)." (PMID 34046336, 2021). "In this work, we demonstrated that VWF is a component of PLT cargo and is released in the GBM tumor mass after TCIPA, thereby supporting a self-sustaining vicious cycle." (PMID 31991805, 2020).